AK3 (adenylate kinase 3)
Description:
Mitochondrial adenylate kinase with a specific GTP:AMP phosphotransferase activity. Could also use ITP as phosphate donor. Its physiological function is to recycle GTP into GDP which is necessary for the TCA cycle in the mitochondrial matrix (Probable).
Synonyms: AK3L1; AK6; AKL3L; AKL3L1; FIX
Tractability: Small molecule: a structure with a bound ligand is known. PROTAC: ubiquitination databases record sites on it; its protein half-life has been measured.
Gene: Protein-coding gene on chromosome 9 (4,709,556 to 4,742,043, reverse strand). Ensembl gene ENSG00000147853.
Subcellular location: Mitochondrion matrix
Subcellular location (Human Protein Atlas): Mitochondria
Pathways (Reactome):
Hemostasis: Factors involved in megakaryocyte development and platelet production
Gene Ontology:
Molecular function: AMP kinase activity; nucleoside triphosphate adenylate kinase activity; protein binding; ATP binding; nucleobase-containing compound kinase activity; phosphotransferase activity, phosphate group as acceptor
Biological process: AMP metabolic process; GTP metabolic process; ITP metabolic process; UTP metabolic process; blood coagulation; nucleoside triphosphate biosynthetic process; ADP biosynthetic process; nucleobase-containing small molecule metabolic process
Cellular component: mitochondrion; mitochondrial matrix
Genetic constraint (gnomAD): Loss-of-function variants: 25 observed, 21.74 expected, observed/expected ratio (o/e) 1.15, 90% interval 0.84 to 1.6. The synonymous counts are far from expectation, so gnomAD's model fits this gene poorly and the ratio says little. Missense variants: 399 observed, 271.79 expected, observed/expected ratio (o/e) 1.47, 90% interval 1.35 to 1.6. Synonymous variants: 157 observed, 110.16 expected, observed/expected ratio (o/e) 1.43, 90% interval 1.25 to 1.63.
Homologues: Orthologues: chimpanzee AK3 (99% identical), macaque AK3 (99% identical), mouse Ak3 (93% identical), rat Ak3 (93% identical), guinea pig AK3 (92% identical), pig AK3 (92% identical), rabbit AK3 (89% identical), dog AK3 (79% identical), zebrafish ak3 (64% identical), tropical clawed frog ak3 (59% identical), Drosophila melanogaster Ak3 (48% identical). Paralogues in human: AK4 (58% identical), AK4P3 (58% identical), AK2 (42% identical), AK1 (25% identical), AK5 (25% identical), AK8 (24% identical), CMPK1 (24% identical), AK7 (21% identical), AK9 (20% identical).
Diseases named in the same sentence as AK3 in open-access papers:
AK3 is named in the same sentence as 18 diseases in open-access papers, as found by Europe PMC text mining. Sharing a sentence is not in itself a finding about the gene and the disease. The quoted sentences say what the papers report.
breast carcinoma (6 papers, 2019 to 2025). "In bladder urothelial carcinoma, the decreased expression of AK3 was associated with a worse prognosis, and in breast cancer, decreased AK3 levels were significantly associated with decreased overall survival." (PMID 36982634, 2023). "LARP1 and AK3 are associated with OS in luminal A and luminal B breast cancers." (PMID 31308365, 2019). "Additionally, the suppression of AK3 (as a phosphotransferase and glycolysis-related gene) triggers a cancerous transformation, leading to an uncontrolled cell cycle and growth with a subsequently worse prognosis and shorter survival of patients with breast cancer." (PMID 40535770, 2025). "Conversely, AK3 and CACNA1H are suggested to exert inhibitory effects on breast cancer progression." (PMID 39590319, 2024).
hepatocellular carcinoma (2 papers, 2021 to 2025). A malignant tumor that arises from hepatocytes. "Consistent with our observations, some studies have shown that AK3 is downregulated in lung cancer and hepatoma." (PMID 40535770, 2025).
leukaemia (2 papers, 2017 to 2025). "Moreover, a subsequent study documented significantly lower levels of AK3 expression in thiopurine-resistant human leukaemia cells than in wild-type cells, indicating a role for the AK3 variant in metastasis progression." (PMID 40535770, 2025).
bladder tumors (1 paper, 2016). "AK3 was not previously connected to CLL or any cancer, apart from the finding that deletion of chromosome 9p frequently occurs in bladder tumors, with chromosome 9 carrying AK1, AK2 and AK3." (PMID 27078856, 2016).
cervical cancer (1 paper, 2022). A primary or metastatic malignant neoplasm involving the cervix. "Therefore, in this study, we evaluated the role of AK3 in energy metabolism in cancer cells by creating and analyzing an AK3 knock-out (AK3KO) HeLa cell line derived from cervical cancer cells." (PMID 35457131, 2022).
embryonal carcinoma (1 paper, 2011). A non-seminomatous malignant germ cell tumor characterized by the presence of large germ cells with abundant cytoplasm resembling epithelial cells, geographic necrosis, high mitotic activity, and pseudoglandular and pseudopapillary structures formation. "In addition, AK3 protein was found to increase 10-fold during neural differentiation of P19 embryonal carcinoma cells." (PMID 21698293, 2011).
cancer (5 papers, 2011 to 2026). A tumor composed of atypical neoplastic, often pleomorphic cells that invade other tissues. "Using cancer cell lines, we found that AK3 enzymatic activity inhibited β-catenin signaling and cell proliferation by attenuating nuclear β-catenin accumulation." (PMID 42014691, 2026). "Transcriptome profiling across multiple cancer patient datasets revealed that AK3 and oxidative phosphorylation pathway are highly correlated with Wnt/β-catenin signaling and prognosis of patients." (PMID 42014691, 2026). "There are three Akt isoforms (Akt1, Akt2, Ak3) found in mammalian cells, each with a distinct role in cancer." (PMID 32012648, 2020). "Here we show a direct effect on cancer cells and provide novel evidence that decreased expression of AK3 in the presence of CSC vapor is accompanied with decreased sensitivity of bladder cells to cisplatin and restoration of AK3 sensitizes cells to cisplatin." (PMID 21698293, 2011). "Moreover, AK3 has been reported to sensitize cancer cells that have acquired cisplatin-resistance by exposure to condensed tobacco vapor." (PMID 35457131, 2022). "Hence, the enhanced expression of SOD3 resulting from knocking out AK3 is interesting as a potential factor in suppressing cancer." (PMID 35457131, 2022). "Some of these proteins were previously connected to different cancer types, including CLL, while four other highly expressed proteins were not previously reported to be associated with cancer, and here, for the first time, DDX46 and AK3 are linked to CLL." (PMID 27078856, 2016).
tumor (4 papers, 2005 to 2025). "The SNP rs378117 in AK3 is a promoter variant associated with reduced gene activity and probably serves as a predictor of progressive symptoms and radiological deterioration of the tumour in our cohort." (PMID 40535770, 2025). "The results showed that CACNA1H, IL13RA1, NUP43, PGK1, and SDC1 were highly expressed in tumor samples, while expression of AK3 was significantly decreased." (PMID 34600547, 2021). "AK3 regulates the homeostasis of adenine nucleotide composition and has been proved to have the ability of anti-tumor." (PMID 34600547, 2021). "Six hits in five genes [AK3 (rs378117), TRPM3 (rs1329774 and rs4745058), CDH4 (rs2427043), LINC00504 (rs76228864), and GRIN2D (rs76754767)] were associated with a risk of tumour progression, whereas variants in HPGD (rs45593131) and RC3H2 (rs2792999) were suggested as protective factors." (PMID 40535770, 2025). "However, the expression of AK3/4 among major tumor stages demonstrated that only AK4 possessed a statistical difference." (PMID 35220277, 2022). "Therefore, our analysis did not identify some tumour markers such as POU5F1, FLJ10884 and AK3, because they already were upregulated in the CIS cells." (PMID 15856041, 2005).
infection (3 papers, 2015 to 2025). The state of being infected such as from the introduction of a foreign agent such as serum, vaccine, antigenic substance or organism. "Flies infected with AB trypanosomes had a higher rate of infection (45.6 ± 18.2%) than tsetse infected with ∆ak3 cells and similar to WT values, suggesting that AK3 confers an advantage to trypanosomes in the context of tsetse infection." (PMID 26218532, 2015). "The predominance of AK3 among New Zealand MRSA isolates and the associated resistance to fusidic acid (an antibiotic that has been widely used in topical formulation) poses significant challenges for infection control." (PMID 40709751, 2025). "We reasoned that the disparity in doubling times may be interfering with any affect AK3 absence/presence may have on tsetse infection rates, and proceeded to infect and score for parasite presence at 20 days or more post infection." (PMID 26218532, 2015). "Immunofluorescence assays with simultaneous probing for AK (anti-TcAK) and AK3::Ty1 (anti-Ty1) in trypanosomes extracted from tsetse in infection experiments revealed that no significant genetic drift occurred in the parasite population during the 20 day incubation period leading up to dissection." (PMID 26218532, 2015).
AK3 also shares sentences with these, for which no sentence is quoted: bladder urothelial carcinoma (1 paper); diabetes (1); Insulin resistance (1); lung adenocarcinoma (1); lung carcinoma (1); medulloblastoma (1); Obesity (1); primary immunodeficiency (1); type 2 diabetes (1).